LINGO2 (leucine rich repeat and Ig domain containing 2)
Synonyms: LERN3; LRRN6C
Tractability: Small molecule: it belongs to a druggable protein family. Antibody: UniProt predicts a signal peptide or a membrane-spanning region; its Gene Ontology location is reachable by antibodies, with medium confidence. PROTAC: its protein half-life has been measured.
Gene: Protein-coding gene on chromosome 9 (27,937,617 to 29,213,601, reverse strand). Ensembl gene ENSG00000174482.
Subcellular location: Membrane
Subcellular location (Human Protein Atlas): Cytoplasmic bodies; Nucleoplasm
Gene Ontology:
Molecular function: protein binding; signaling receptor activity
Cellular component: plasma membrane; membrane
Genetic constraint (gnomAD): Loss-of-function variants: 14 observed, 30.65 expected, observed/expected ratio (o/e) 0.46, 90% interval 0.3 to 0.71. The upper end of that interval is the gene's LOEUF score, 0.71, which puts it in group 2 of 6, group 1 being the genes least tolerant of losing a copy. Missense variants: 729 observed, 779.83 expected, observed/expected ratio (o/e) 0.93, 90% interval 0.88 to 0.99. Synonymous variants: 317 observed, 301.1 expected, observed/expected ratio (o/e) 1.05, 90% interval 0.96 to 1.15.
Homologues: Orthologues: chimpanzee LINGO2 (99% identical), macaque LINGO2 (99% identical), pig LINGO2 (99% identical), rabbit LINGO2 (98% identical), mouse Lingo2 (98% identical), rat Lingo2 (98% identical), guinea pig LINGO2 (97% identical), tropical clawed frog LINGO2 (79% identical), zebrafish lingo2a (64% identical), zebrafish lingo2b (53% identical). Paralogues in human: LINGO1 (60% identical), LRRN1 (27% identical), LRRN3 (24% identical), LRRN2 (23% identical), SLIT1 (23% identical), SLIT2 (22% identical), TLR9 (22% identical), LRFN1 (21% identical), LRFN2 (21% identical), LRFN3 (21% identical), LRFN4 (21% identical), LRFN5 (21% identical), and 13 more.
Diseases named in the same sentence as LINGO2 in open-access papers:
LINGO2 is named in the same sentence as 36 diseases in open-access papers, as found by Europe PMC text mining. Sharing a sentence is not in itself a finding about the gene and the disease. The quoted sentences say what the papers report.
essential tremor (10 papers, 2013 to 2024). A relatively common disorder characterized by a fairly specific pattern of tremors which are most prominent in the upper extremities and neck, inducing titubations of the head. "LINGO1 and LINGO2 are associated with increased risk of essential tremor and Parkinson’s disease, and a single nucleotide polymorphism of LINGO2 is associated with increased risk of AD." (PMID 38918213, 2024). "The single nucleotide polymorphisms in intronic regions of LINGO2 has been verified to be linked to essential tremor and Parkinson’s disease, which are neurodegenerative disorders." (PMID 33920310, 2021). "When checking the association between genes and clinical severity of ASD, LINGO2 is of note, which has been verified to be linked to neurodegenerative disorders, such as essential tremor and Parkinson’s disease." (PMID 33920310, 2021). "LINGO2 has been implicated in Parkinson’s disease and essential tremors (a disorder of the nervous system)." (PMID 29479499, 2018). "Diseases associated to SLC1A1 (OMIM: 133550) include Dicarboxylic Aminoaciduria and susceptibility to Schizophrenia, while LINGO2 (OMIM: 609793) has variants associated with essential tremor and Parkinson disease and also has an intronic SNP associated with body mass." (PMID 30677042, 2019). "LINGO1 and LINGO2 are associated with essential tremor and Parkinson’s disease; however, the function of LINGO2 in carcinogenesis is unknown." (PMID 30696080, 2019). "In human Lingo2 been linked both to essential tremor and to Parkinson’s disease." (PMID 24427155, 2013). "Single nucleotide variants in the LINGO2 gene have been associated with essential tremor and with Parkinson's disease, suggesting that the LINGO2 protein may have a neurological function." (PMID 23341896, 2013). "Interestingly, LINGO2 is a member of LRR gene family that, along with LRRK2, has been linked to Essential tremor (ET) and PD and has even become a promising therapeutic target in multiple sclerosis (MS) and PD." (PMID 33493177, 2021).
Parkinson disease (10 papers, 2013 to 2024). A progressive degenerative disorder of the central nervous system characterized by loss of dopamine producing neurons in the substantia nigra and the presence of Lewy bodies in the substantia nigra and locus coeruleus. "The expression of leucine-rich repeat and immunoglobulin-like domain-containing nogo receptor-interacting protein 2 (LINGO2) has been reported in Parkinson’s disease; however, its role in other diseases is unknown." (PMID 30696080, 2019).
gastric cancer (6 papers, 2019 to 2025). A primary or metastatic malignant neoplasm involving the stomach. "We identified LINGO2 as a CSC-associated protein in gastric cancers both in vitro and in patient-derived tissues." (PMID 30696080, 2019). "LINGO2 is a stem cell marker associated with poor prognosis in gastric cancer." (PMID 40672387, 2025). "LINGO2 (leucine rich repeat and Ig domain containing two) encodes a transmembrane protein that was recently reported as a cancer stem cell (CSC) marker and oncogene in gastric cancer; high expression of LINGO2 was associated with increased cell motility, angiogenic capacity, and tumorigenicity." (PMID 33371395, 2020). "Therefore, LINGO2 was highly suspected to be associated with the development and growth of gastric cancer as well as the progression of gastric cancer from early to late stage." (PMID 30696080, 2019). "LINGO2, a stem cell-related marker, has been demonstrated to correlate with worse prognosis in gastric cancer (GC) patients." (PMID 40672387, 2025). "Recently, researchers have proposed the role of CSC-associated protein, leucine-rich repeat and immunoglobulin-like domain-containing nogo receptor-interacting protein 2 (LINGO2), in gastric cancer and EMT initiation." (PMID 32340207, 2020). "Our data suggest that LINGO2 is a new therapeutic target for gastric cancer which targets EMT as well as CSC." (PMID 30696080, 2019). "This is the first study to demonstrate the role of LINGO2 and its expression in human gastric cancer tissues." (PMID 30696080, 2019). "To determine the functional role of LINGO2, we suppressed LINGO2 expression in gastric cancer cell line SNU484 using shRNA." (PMID 30696080, 2019). "In our studies, we explored the role of LINGO2 as a regulator of cell motility and stemness in gastric cancer cells." (PMID 30696080, 2019). "Tissue microarray analysis showed that LINGO2 expression was significantly elevated in advanced gastric cancers." (PMID 30696080, 2019). "These indicate the involvement of LINGO2 in gastric cancer initiation and progression by altering cell motility, stemness, and tumorigenicity, suggesting LINGO2 as a putative target for gastric cancer treatment." (PMID 30696080, 2019). "We evaluated the LINGO2 expression in 103 samples human gastric cancer by immunohistochemistry (IHC)." (PMID 30696080, 2019). "In this study, we found that LINGO2 is expressed in gastric cancer tissues and regulates cell motility, tumorigenesis, and angiogenesis." (PMID 30696080, 2019). "Furthermore, novel functions of LINGO2 in regulating cell migration, stemness, MMPs, tumorigenic ability, and angiogenesis were demonstrated, as well as the first clinical implication of LINGO2 expression correlated with gastric cancer progression." (PMID 30696080, 2019). "Our study reports for the first time that LINGO2 expression is elevated in stemness-enriched cells in gastric cancer cell lines, based on cDNA microarray analysis, and evaluation of tissues derived from gastric cancer patients." (PMID 30696080, 2019). "We observed different levels of LINGO2 expression in all gastric cancer patients." (PMID 30696080, 2019). "LINGO2 expression was significantly increased in patients with advanced gastric cancer." (PMID 30696080, 2019). "However, this may lead to carcinogenic behavior; tissue microarray analysis revealed that LINGO2 expression was significantly increased in advanced gastric cancer, and the overall survival rate of patients with high LINGO2 was significantly lower than that of patients with low LINGO2." (PMID 35039476, 2022).
autism (4 papers, 2013 to 2020). Persistent deficits in social interaction and communication and interaction as well as a markedly restricted repertoire of activity and interest as well as repetitive patterns of behavior. "There were 3 VUS inherited from asymptomatic parents intersecting with genes within CNVs that have previously been implicated with disorders, such as CACNA2D1 with epilepsy and ID, and MACROD2 and LINGO2 with autism." (PMID 29441128, 2018). "Deletions affecting the LINGO2 gene have been reported in a cohort of Utah autism patients." (PMID 24690944, 2014).
colitis (4 papers, 2019 to 2024). Inflammation of the colon. "Excessive basal EGFR activation in Lingo2 deficient mice increases disease severity during colitis and augments immunity against helminth infection." (PMID 31562318, 2019). "Lingo2 knockout mice are highly susceptible to experimental colitis." (PMID 36704785, 2022). "In support of this hypothesis, the increased disease severity of DSS colitis in LINGO2 deficient mice and their resistance to N.b." (PMID 31562318, 2019). "LINGO2 deficiency basally elevates EGFR activity, susceptibility to colitis and resistance to helminth infection." (PMID 31562318, 2019). "Our data support a model wherein TFF3 produced by goblet cells can bind the LINGO2 extracellular domain (NH2 terminal 350 AA) to de-repress inhibitory LINGO2-EGFR complexes, thereby allowing TFF3 to help maintain mucosal barrier integrity, suppress colitis, and promote immunity against GI helminths." (PMID 31562318, 2019).
Obesity (4 papers, 2017 to 2025). Accumulation of substantial excess body fat. "Genome-wide association studies (GWASs) showed that different SNPs in LINGO2 were associated with obesity, T2D, and gestational diabetes mellitus risk." (PMID 40070201, 2025). "Genetic variants in several genes, including SLC9A2, ELAVL4 and LINGO2, are associated with both obesity and Blautia abundance, which could suggest that the mechanism of these variants acts through the gut microbiome." (PMID 32580458, 2020). "SNPs annotated to genes previously associated to obesity traits (LINGO2, NELL1) and neurological disorders (schizophrenia (ACSM1, KIF26B, NALCN)), and alcohol and nicotine dependence (LINGO, SH3BP5) were found among Prudent reported dietary pattern score associated-SNPs." (PMID 28644415, 2017). "Overall, a number of interesting genes that could play a role in obesity susceptibility have been identified within these CNVs (e.g. ASTN2, APOA2, PARK2, LINGO2, PLCB1, PTEN, and CIDEA)." (PMID 29441128, 2018).
epilepsy (2 papers, 2018). A brain disorder characterized by episodes of abnormally increased neuronal discharge resulting in transient episodes of sensory or motor neurological dysfunction, or psychic dysfunction. "In addition to LINGO2, 13 other genes identified in the syntenic region are also associated with ALS, FTD or some form of neuronal/nervous disorder like spinocerebellar ataxia and epilepsy." (PMID 29479499, 2018).
gestational diabetes (2 papers, 2022 to 2025). Carbohydrate intolerance first diagnosed during pregnancy. "The LINGO2 variant detected in the Chinese population may increase the risk of gestational diabetes." (PMID 35309141, 2022).
helminth infection (2 papers, 2019 to 2025). "This indicated that Lingo2 deficiency protected against helminth infection, at least in part, due to EGFR activity." (PMID 31562318, 2019). "Moreover, LINGO2 has been related to immunity against helminth infection." (PMID 40070201, 2025).
nicotine dependence (2 papers, 2017 to 2022). Physical and psychological dependence on nicotine. "FTO and LINGO2 have suggestive associations with nicotine dependence." (PMID 35613103, 2022).
adenoma (1 paper, 2019). A neoplasm arising from the epithelium. "A more interesting finding was that LINGO2 expression was barely detected in both normal gastric tissues and adenomas polyp tissues, but a moderate expression, though not as strong as in cancer tissues, was observed in SPEM region in non-tumor gastric tissues." (PMID 30696080, 2019).
Alcoholism (1 paper, 2018). "LINGO2 (9p21.1) was reported to be associated with age at onset of alcohol dependence in the Collaborative Study on the Genetics of Alcoholism." (PMID 29912962, 2018).
asthma (1 paper, 2016). "This leucine-rich repeat and Ig domain-containing 2 (LINGO2) gene is not known to be implicated in asthma." (PMID 27445529, 2016). "This study also suggests a potential role for new loci, namely, SYNE1, LINGO2, and IFNG-AS1, in the pathogenesis of asthma." (PMID 27445529, 2016).
breast carcinoma (1 paper, 2023). "Studies in mouse embryos have shown expression of LINGO2 specifically in the central nervous system, but it has not been implicated in breast cancer to date." (PMID 37559094, 2023).
chronic obstructive pulmonary disease (1 paper, 2016). A chronic and progressive lung disorder characterized by the loss of elasticity of the bronchial tree and the air sacs, destruction of the air sacs wall, thickening of the bronchial wall, and mucous accumulation in the bronchial tree. "A recent study found that SNPs flanked by LINGO2 were associated with airway responsiveness in chronic obstructive pulmonary disease." (PMID 27445529, 2016).
developmental delay (1 paper, 2022). "Copy number variants of LINGO2 have been found in ASD cases, and LINGO2 deletions have been reported in individuals with developmental delay, autistic behavior, and craniofacial abnormalities." (PMID 36310845, 2022).
endometrial cancer (1 paper, 2017). Primary or metastatic malignant neoplasm involving the endometrium (mucous membrane that lines the endometrial cavity). "Recently, LINGO2 was found to be associated with endometrial cancer." (PMID 29036934, 2017).
gastric polyp (1 paper, 2019). "The expression of LINGO2 was barely detected in normal gastric tissues and gastric polyp tissues while moderate expression was observed in SPEM tissues." (PMID 30696080, 2019).
cancer (9 papers, 2019 to 2025). A tumor composed of atypical neoplastic, often pleomorphic cells that invade other tissues. "Given that the functional role of the top one down‐regulated protein LINGO2 (leucine rich repeat and Ig domain containing 2) following C9orf142 knockdown in human cancer is ambiguous, we selected MTBP, the second down‐regulated protein following C9orf142 knockdown, for further verification." (PMID 38009308, 2023). "We propose that therapeutic targeting of LINGO2 may contribute to target gastric CSC to overcome conventional cancer therapy." (PMID 30696080, 2019). "While its direct role in LUAD is underexplored, LINGO2 overexpression correlates with EMT and immune evasion in pan-cancer analyses." (PMID 40672387, 2025). "Although LINGO2 gene was identified as a CSC marker from cancer cells and cancer sphere cells, it is possible that non-tumor cells also express LINGO2." (PMID 30696080, 2019).
tumor (6 papers, 2012 to 2025). "In our study, LINGO2 was downregulated in BRAFwt PTCs and even more in BRAFmut PTCs compared to TN samples which may imply a tumor suppressor function for this molecule." (PMID 25922907, 2015). "The elevated expression of pVEGFR2 and CD34 in LINGO2high tumor tissues and the inhibition of HUVEC tube formation by cell culture supernatant from LINGO2-silenced cell supernatant which further supports the involvement of LINGO2 in angiogenesis." (PMID 30696080, 2019).
neurological disorders (4 papers, 2017 to 2024). "On the basis of existing research and our analysis results, we speculate that LINGO2 may show specific expression patterns at different stages of neurodevelopment and species evolution, which may provide references for interpreting neurological disorders." (PMID 35309141, 2022).
neurodegenerative disease (2 papers, 2022 to 2024). A disorder of the central nervous system characterized by gradual and progressive loss of neural tissue and neurologic function. "The results of a large number of Asian population studies showed that LINGO2 may be a susceptibility gene for ET and Parkinson’s syndrome and that the increased expression of LINGO is a characteristic pathological response of neurodegenerative diseases." (PMID 35309141, 2022). "In addition, the LINGO2 mutant may be an important indicator of neurodegenerative diseases." (PMID 35309141, 2022).
LINGO2 also shares sentences with these, for which no sentence is quoted: schizophrenia (2 papers); Adult onset (1); Alzheimer disease (1); cardiomyopathy (1); dicarboxylic aminoaciduria (1); familial Alzheimer disease (1); gastric tumor (1); gastrointestinal disease (1); malignant mesothelioma (1); multiple sclerosis (1); neuroblastoma (1); Parkinson’s (1); polyp (1); spinocerebellar ataxia (1).